LEP (leptin)
Diseases named in the same sentence as LEP in open-access papers (continued):
Sharing a sentence is not in itself a finding about the gene and the disease.
cancer (continued). "Future investigations are needed to provide an insight into the connection between autophagy and amino acid metabolism modulated by adiponectin and leptin in cancer cells." (PMID 33535537, 2021). "Several research articles from our group have shown that IL-6 levels in advanced cancer patients correlate with leptin, the main marker of body composition and nutritional status." (PMID 33809200, 2021). "Emerging evidence has shown the oncogenic roles of leptin in modulating cancer progression in addition to its original roles." (PMID 33804101, 2021). "Taken together, leptin reconstructs cancer cellular lipid metabolism by multifactorial modulating biosynthesis and utilization of lipids, which further facilitate tumor progression." (PMID 34888248, 2021). "Studies have found that globular adiponectin (gAcrp) can inhibit the activation of leptin inflammatory bodies through heme oxygenase-1 (HO-1) signaling, thus preventing the cancer-promoting effect of leptin." (PMID 34485124, 2021). "Emerging evidence has demonstrated leptin’s roles in regulating cancer progression, including tumor proliferation, metastasis, angiogenesis, and drug resistance." (PMID 33804101, 2021). "The impact of leptin treatment on cancer cell proliferation varies greatly from one type of cells to the other." (PMID 34588926, 2021). "To date, a large body of evidence supports the view that adiponectin and leptin are critical drivers of glucose and lipid metabolism, whereby they differentially modulate cancer development and progression." (PMID 33535537, 2021). "In contrast to the protective role of leptin and visfatin, adiponectin promotes ROS production, leading to redox imbalance and apoptosis in cancer cells." (PMID 33535537, 2021). "While leptin imparts a survival advantage to growing cancer cells, adiponectin acts quite the opposite." (PMID 33450975, 2021). "Leptin was reported to be a gene characteristic of G2 and G3 cancer, and its overexpression increased with EC grade." (PMID 34202922, 2021). "Leptin exerts many different actions on various tissues and systems, including cancer, and is considered as a linkage between metabolism and the immune system." (PMID 34202969, 2021). "Our results shed light on the role of leptin in cancer and provide guidance and potential directions for further research for scientists in this field." (PMID 33799880, 2021). "While leptin is known to be tumor promoting, adiponectin has been shown to be protective against cancer." (PMID 33450975, 2021). "A recent study has also reported that cellular metabolic reprogramming contributes to leptin‐induced proliferation and survival of cancer cells." (PMID 33226729, 2021). "Previous works have shown the expression of leptin and Ob-R in epithelial cells of normal and cancer colon using various methods (Western blotting, RT-PCR and immunohistochemistry)." (PMID 33159578, 2021). "Consistently, pretreatment with fatostatin or TVB‐3166, which are pharmacological inhibitors of SREBP‐1 and FASN, respectively, also impeded cancer cell growth promoted by leptin." (PMID 33226729, 2021). "Mechanistically, activation of PI3K/Akt seems to play a critical role in leptin-driven glucose metabolism in cancer cells." (PMID 33535537, 2021). "The development of leptin signaling modulators represents a promising strategy for the treatment of cancers and other leptin-related diseases." (PMID 34356668, 2021). "Taken together, these findings support the notion that leptin drives fatty acid metabolic rewiring toward increased abundance of intracellular lipids, which in turn promotes cancer progression." (PMID 33535537, 2021). "Taken together, these results highlighted a crucial role of autophagy in leptin‐induced cancer cell‐specific metabolism, which is mediated, at least in part, via SREBP‐1 induction." (PMID 33226729, 2021).
cancer (continued). "Contrarily, adiponectin has anti-cancer effects, and similarly to leptin, its expression in mAT is greater than in WAT, especially in cancer patients." (PMID 33670492, 2021). "Pathophysiological mechanisms of cancer such as inflammation, invasion, and metastasis are also favored by LEP." (PMID 34868961, 2021). "A meta-analysis was conducted to precisely verify the relationships between LEP G19A and the development of digestion-related cancers." (PMID 34868961, 2021). "Some studies have also indicated that leptin and ObR are overexpressed in primary and metastatic invasive ductal breast carcinoma cells, compared with non-cancer mammary tissue." (PMID 34485137, 2021). "It is noteworthy that adiponectin antagonizes the oncogenic actions of leptin, supporting the epidemiological evidence that aberrant secretion of adipokines would results in development of cancer." (PMID 33535537, 2021). "Active physical activity can not only reduce the risk of cancer by reducing weight but also reduce the cancer risk by reducing the level of insulin, IGF-1, IGF-binding protein 3 and leptin in the body." (PMID 35083251, 2021). "Previous studies indicated that leptin increased oxygen consumption rate and promoted mitochondrial β‐oxidation in cancer cells." (PMID 33226729, 2021). "It is surprising that while leptin has been well known as a suppressor of SREBP‐1 in liver and adipose tissues, little is known about contributions of SREBP‐1 to the effects of leptin on cancer‐specific metabolism and tumor growth." (PMID 33226729, 2021). "Clinical studies indicated a positive correlation between leptin:adiponectin ratio and increased risks for some cancers like ECa in post-menopausal women, BCa and PCa." (PMID 34354670, 2021). "Recently, the LEP protein was shown to promote cancer progression and metastasis by regulating the epithelial–mesenchymal transition (EMT), cell adhesion to the extracellular matrix (ECM), and proteolysis of the ECM components." (PMID 34884678, 2021). "It was also suggested that leptin shifts the mode of energy production in cancer cells, from glucose consumption to the utilization of fatty acids, thereby favoring the use of glucose for biosynthesis." (PMID 33535537, 2021). "Their primary disadvantage is the exclusion of potential peripheral effects of leptin on cancer cells and the cells of the tumor microenvironment." (PMID 33987528, 2021). "Leptin, derived from adipocytes, has been suggested to contribute to the growth of cancer cells; however, the detailed mechanism of leptin in GBC drug resistance remains uninvestigated." (PMID 34156978, 2021). "Leptin supports cancer cell survival by inhibiting the apoptotic pathways through downregulating Bad, tumor necrosis factor alpha receptors 1 (TNFR1) and caspase 6 expression." (PMID 34588926, 2021). "The resultant upregulation of survivin promotes the migration and invasion of cancer cells, suggesting a direct role of leptin-Notch-EGFR axis in leptin induced metastasis." (PMID 34588926, 2021). "For example, the activation of the cAMP pathway enhanced the apoptosis of cancer cells in oncolytic virotherapy, and Leptin enhanced the anti-proliferative effect of cAMP elevating agents." (PMID 33777791, 2021). "Circulating leptin levels or leptin/Ob-R expression also promote both the survival and proliferation of tumor cells in other types of cancer." (PMID 34202969, 2021). "Our purpose is to review this dual role of leptin in cancer, as well as trying to clarify the future perspectives of this adipokine, which further highlights its importance as a cornerstone of the immunometabolism in oncology." (PMID 34202969, 2021). "In cell culture experiments, leptin enhanced mammosphere formation, and the pro-cancer effects including cell viability, migration, invasion, and CSC- and EMT-related gene expression." (PMID 34350120, 2021). "Leptin treatment appeared to promote cancer cell migration and EMT transition by activating the STAT3 pathway." (PMID 33799880, 2021).
cancer (continued). "Knowledge-based analysis by IPA indicated the induction of cancer cell migration by leptin, which was manifested via direct leptin treatment in the RCC cell lines." (PMID 33804101, 2021). "The potential regulation of leptin toward cancer cell migration and invasion was identified and listed (top three diseases and functions)." (PMID 33804101, 2021). "The leptin involvement in body weight regulation, immunity, angiogenesis, and cancers has generated a great interest in the design and development of different leptin and ObR-based therapeutic approaches." (PMID 34356668, 2021). "VEGF is well known to promote the migration of endothelial cells, and leptin and is reported to induce the migration of cancer cells." (PMID 34552037, 2021). "Leptin promotes the utilization of glucose for glycolysis and biosynthesis, whereas adiponectin reverses, at least in part, the Warburg effect in cancer cells." (PMID 33535537, 2021). "An obese environment increases tumor-recruitment of ASCs, which promote cancer cell growth, possibly via leptin secretion." (PMID 33710603, 2021). "Recent work has identified specific cell types other than adipocytes that harbor leptin and leptin receptor expression, particularly in cancers and tumor microenvironments, and characterized the role of this signaling axis in cancer progression." (PMID 33799880, 2021). "The recent evidence not only supports the possible role of leptin in the initiation of cancer, but it has also been confirmed to promote the invasion and metastasis of cancer cells by activating EMT, inhibiting immune checkpoints and bolstering angiogenesis." (PMID 34588926, 2021). "Researchers showed that inhibiting or silencing SREBP-1 or FASN impeded cancer cell viability promoted by leptin." (PMID 34888248, 2021). "For instance, the co-treatment of MDA-MB231 cells with leptin and cAMP elevating agents (8-pCPT-2′-O-Me-cAMP, 8-Br-cAMP) blocked the proliferative effect of leptin and induced apoptosis in cancer cells by downregulating Bcl2." (PMID 34588926, 2021). "Among the pathophysiological mechanisms of cancer, LEP seems relevant to the proliferation of cancer stem cells." (PMID 34868961, 2021). "Blockage of PI3K by a selective pharmacological inhibitor (LY294002) led to abrogation of alterations in glucose metabolism, as well as malignant behaviors promoted by leptin in cancer cells." (PMID 33535537, 2021). "Because of the activation of these signaling pathways, the leptin–Ob-R axis increases the proliferation, migration, and invasion of cancer cells and to contribute to the release of vascular endothelial growth factor." (PMID 34868066, 2021). "The resultant activation of Notch signaling further accounts for the leptin-induced cell proliferation in cancer." (PMID 34588926, 2021). "The crosstalk between leptin signaling and other inflammatory cytokines could explain why patients do not exhibit increased appetite or lower energy expenditure, despite decreased levels of leptin in many disease-associated cachexic states such cancer, COPD, and aging." (PMID 34440723, 2021). "The downstream effects of leptin signaling can induce malignancies via the activation of specific signaling pathways in cancer cells." (PMID 33799880, 2021). "The important adipokine leptin was also shown to make use of the JAK-STAT3 pathway to induce cancer stemness and evade immune surveillance." (PMID 34122412, 2021). "This notion is supported by the evidence showing that HIF1α is a critical driver of the Warburg effect and that leptin stabilizes HIF1α in cancer cells." (PMID 33535537, 2021). "Leptin-induced cancer cell migration, invasion and metastasis were also observed in a pancreatic orthotopic model." (PMID 33799880, 2021). "We validated these results by analyzing the data surrounding LEP expression in different types of cancers generated by GEPIA using TCGA data." (PMID 34414945, 2021).
cancer (continued). "Leptin, for instance, promotes migration of BC cells to the bone marrow niche, as well as oncogenesis and proliferation of cancer cells within the niche." (PMID 33670492, 2021). "The first inhibitory effect of leptin treatment in human cancer cell lines was reported in Mia-PaCa and PANC-1 pancreatic cells." (PMID 34202969, 2021). "High adiponectin levels can also inhibit the progression of colorectal cancer by interfering with the cancer-promoting effect of leptin." (PMID 34485124, 2021). "The serum levels of cytokines, insulin, ghrelin, leptin, adiponectin, cortisol, and thyroid hormones were altered during cancer progression and the CCRT course." (PMID 34578846, 2021). "Among various adipokines, leptin and adiponectin have been documented to modulate lipid metabolism in cancer cells in a complicated manner." (PMID 33535537, 2021). "We confirmed these findings and demonstrated that leptin-induced autophagy is involved in the cancer-promoting features induced by leptin." (PMID 33763424, 2021). "Yet, the mechanisms by which autophagy stimulated by leptin and adiponectin differentially modulates cancer cell fate are poorly understood." (PMID 33535537, 2021). "In pancreatic cancer, leptin is highly expressed and increases cancer stem cell phenotypes, proliferation, migration and chemoresistance." (PMID 33536560, 2021). "First, since FAO represents a model of high-efficiency energy production, FAO induction by leptin leads to elevated production of ATP to fuel cancer cell growth." (PMID 33535537, 2021). "The demonstrations of main biological effects and signaling axes induced by leptin/leptin receptor in different cancer types were shown." (PMID 33799880, 2021). "MAPK signaling was activated to induce AP-1 binding to the VEGF-A promoter and initiate transactivation upon stimulation of the leptin-leptin receptor signaling axis in cancer cells." (PMID 33799880, 2021). "Leptin and leptin receptor are also involved in the development of various cancers like breast, thyroid, colon, and prostate cancers through pathways that promote proliferation, cell migration and invasion." (PMID 34356668, 2021). "Leptin, a hormone mainly derived from adipocytes, shows pleiotropic effects on regulating energy balance and cancer progression." (PMID 34888248, 2021). "There has been increasing attention to the relationship between cancer and leptin, which is abundant in adipose tissue." (PMID 34745135, 2021). "Tumors from obese mice had higher expression of cancer stem cell-associated genes, such as FOXC2 and TWIST2, while higher levels of the leptin expression found in the surrounding obese mammary fat pads." (PMID 34912237, 2021). "Among the adipokines, Acrp30 and leptin gained great attention since their serum levels have been found deregulated in different human cancers." (PMID 33587254, 2021). "On the other hand, adipocytes interact with cancer cells mainly through adipokine secretion, such as IL-6 or Leptin, or through the modulation of cancer cell metabolism." (PMID 34359819, 2021). "The leptin signaling also suppresses mitochondrial respiration in cancer cells, an act that further promotes invasion, metastasis and enhances the survival of these defiant cells under hypoxic conditions." (PMID 34588926, 2021). "Leptin has also been reported to stimulate the proliferation of T cells in vitro, as well as activating DC, thus promoting the cancer-immunity cycle." (PMID 34202969, 2021). "Leptin can also act as a pro-angiogenic and proinflammatory agent, which increases the initiation and progression of cancer." (PMID 33864589, 2021). "It is thereby suggested that leptin is not only involved in tumorigenesis, it also contributes to the resistance of cancer cells against chemotherapy." (PMID 34588926, 2021). "Upon binding to Ob-Rs, leptin promotes cancer cells survival, proliferation, and metastasis, activating several signaling pathways, including MAPK/ERK, PI3K/Akt, and Janus kinase (Jak)-STAT signaling." (PMID 34681797, 2021).
cancer (continued). "The inflamed adipocytes secrete various adipocytokines notably IL-6 and leptin that enhance carcinoma growth." (PMID 34561446, 2021). "The signaling in several types of cancer cells is sustained by adipokines secreted by adipocytes, mainly including leptin, adiponectin, oestrogens, insulin-like growth factor 1 (IGF-1) and hepatocyte growth factor (HGF)." (PMID 32854444, 2020). "The human small RNA miR-4443 is functionally involved in several types of cancer and in the biology of the immune system, downstream of insulin and leptin signaling." (PMID 32069948, 2020). "We observed that bone metastatic tissue stained for leptin in cancer cells and stromal cells: leptin is one of the many microenvironmental factors that act on metastatic cells, as occurs in the mammary glands." (PMID 33213024, 2020). "Subsequently, PAI-1- knockdown cancer cells were exposed to leptin (100 ng/mL, 72 h) and measured with migration assays for 12 h." (PMID 33371368, 2020). "Consistently, our data revealed that leptin reversed PAI-1 depletion-induced attenuation of cancer cell migration." (PMID 33371368, 2020). "Leptin is a peptide hormone produced and secreted mainly by adipose cells, playing a crucial role in reproduction, appetite, and cancer environment." (PMID 33255835, 2020). "Our results extended these previous findings by demonstrating a direct involvement of leptin in sustaining cancer stem-like properties in GBM cells." (PMID 32526957, 2020). "During the last 10 years, the role of leptin in promoting the expansion of cancer stem cells has been reported in breast and other cancers." (PMID 32526957, 2020). "Strikingly, STAT3 depletion-induced miR-34a upregulation was abrogated by further leptin stimulation in cancer cells, implying that miR-34a is a signaling factor mediating the indirect effect of STAT3 on PAI-1 downstream of leptin/OBR." (PMID 33371368, 2020). "Leptin mediates its role by binding to the leptin receptor (obRa-obRf), a class 1 cytokine receptor present in breast cells and overexpressed in cancer." (PMID 32796696, 2020). "Further research has also found that leptin also plays critical roles in promoting key processes in cancer including metastasis, proliferation, and even drug resistance." (PMID 32742493, 2020). "Since anorexia, hyper-metabolism, and inflammatory acute phase response play a role in the development of cancer cachexia, increased leptin secretion has been suggested to be involved in the onset of this pathology." (PMID 32660156, 2020). "The implications of leptin signaling on chemoresistance in BC and other obesity-related cancers are not well understood." (PMID 32471192, 2020). "There are a variety of other observations that link leptin and thyroid hormone together at cancer cells." (PMID 32645835, 2020). "Numerous studies and epidemiological data have indicated the role of adipokines (particularly leptin) in the development and the progression of cancer." (PMID 32573960, 2020). "Accumulating evidences suggest that leptin induces EMT in cancer cells via different molecular pathways including JAK/STAT pathway, β-catenin activation via Akt/GSK3 and MTA/Wnt1 pathway, and activation of IL-8 via PI3K/Akt dependent pathway." (PMID 33511131, 2020). "In this context, the crosstalk between leptin and Notch pathways has been described in breast, pancreatic, and endometrial cancers, where it affects cell proliferation, migration, invasion, angiogenesis, and chemoresistance." (PMID 32526957, 2020). "Elevated expression of leptin and resistin was found to regulate the response of cancer cells to chemotherapy." (PMID 32489325, 2020). "Exercise has a significant effect on serum leptin of obese individuals although leptin levels in cancer patients seem to be controversial." (PMID 33371214, 2020). "The role of leptin in tumorigenesis was suggested by the high expression of its receptor (ObR) in several cancer cells." (PMID 32120856, 2020).